BRCA2 (BRCA2 DNA repair associated)
Diseases named in the same sentence as BRCA2 in open-access papers (continued):
Sharing a sentence is not in itself a finding about the gene and the disease.
Hereditary breast and ovarian cancer syndrome (continued). "Today, genetic testing for Hereditary Breast Ovarian Cancer syndrome has moved from testing of the BRCA1 and BRCA2 genes to broader panel testing." (PMID 28281021, 2017). "In the 1990s, linkage analyses and positional cloning in breast and breast-ovarian cancer families led to the identification of BRCA1 and BRCA2." (PMID 25848941, 2015). "However, not all breast and breast-ovarian cancer families carry a mutation in BRCA1 or BRCA2." (PMID 25848941, 2015). "Here, we performed comprehensive genetic testing of BRs to identify any PGV from among 30 causative genes associated with HBOC syndrome, regardless of PGV positivity status of the BRCA1/BRCA2 wild-type proband." (PMID 39003386, 2024). "Thirty-nine patients (2%) were identified as carriers of a PV in an autosomal dominant clinically actionable hereditary breast and ovarian cancer (HBOC)-related or Lynch syndrome gene, most frequently, BRCA2 (6/39; 15.4%), PALB2 (8/39; 20.5%), CHEK2 (10/39; 25.6%), and PMS2 (5/39; 12.8%)." (PMID 37861889, 2024). "All patients met the clinical criteria for hereditary breast and ovarian cancer syndrome (HBOC) and were negative for BRCA1 and BRCA2 mutations." (PMID 35625568, 2022). "BRCA phenocopies are individuals with the same phenotype (i.e. cancer consistent with Hereditary Breast and Ovarian Cancer syndrome = HBOC) as their affected relatives, but not the same genotype as assessed by blood germline testing (i.e. they do not carry a germline BRCA1 or BRCA2 mutation)." (PMID 31346352, 2019).
Lynch syndrome (126 papers, 2014 to 2026). An autosomal dominant hereditary neoplastic syndrome characterized by the development of colorectal carcinoma and a high risk of developing endometrial carcinoma, gastric carcinoma, ovarian carcinoma, renal pelvis carcinoma, and small intestinal carcinoma. "Bilateral salpingo-oophorectomy (BSO) is the standard risk-reducing intervention recommended for individuals carrying germline mutations in the BRCA1 or BRCA2 genes, as well as for those with other high-risk gene mutations or a diagnosis of Lynch syndrome." (PMID 41463165, 2025). "For women carrying mutations in high-risk genes such as BRCA1, BRCA2, or mismatch repair genes associated with Lynch syndrome, risk-reducing salpingo-oophorectomy (RRSO) and hysterectomy are established strategies endorsed by major guidelines." (PMID 40565763, 2025). "Of the 1474 patients who underwent genetic testing, PVs were identified in 123 individuals, including 76 actionable PVs (5.2%), of which 17 were in BRCA1 or BRCA2 and 11 were in Lynch syndrome–associated genes (eTable 4 in Supplement 2)." (PMID 40053353, 2025). "Individuals with cancer susceptibility syndromes such as BRCA1, BRCA2, and Lynch syndrome mutations face a greater lifetime risk of developing endometrial, ovarian, fallopian tube, and peritoneal cancers." (PMID 38698439, 2024). "Patients with P/LP variants in BRCA1, BRCA2, or Lynch syndrome carriers face lifetime cancer risks of 20%–80%, including breast, ovarian, colon, and endometrial cancer." (PMID 38163482, 2023). "Hereditary breast and ovarian cancer syndrome is frequently associated with germline mutations in the BRCA1 and BRCA2 genes, whilst Lynch syndrome is categorised by germline mutations in DNA mismatch repair genes." (PMID 33673083, 2021). "When an individual is found to have a germline BRCA1/BRCA2 mutation in HBOC or a DNA mis-match repair gene mutation in Lynch syndrome, the individual should inform their at-risk family members about the option of presymptomatic DNA testing." (PMID 34525964, 2021). "High risk consisted of >1 first‐degree relatives with PC or PC‐associated mutations (i.e. BRCA2, Lynch Syndrome, Familial Atypical Multiple Mole Melanoma Syndrome, STK11, or PALB2)." (PMID 33319059, 2020). "Half of the detected pathogenic/likely pathogenic variants were found in BRCA1 (23%), BRCA2 (23%), or the Lynch syndrome-associated genes PMS2 (4%) and MLH1 (2%)." (PMID 32090079, 2020). "A 56-year-old woman suspected of having Lynch syndrome was identified as a BRCA2 pathogenic variant carrier by multigene panel testing." (PMID 33489693, 2020). "Select syndromes are relatively prevalent genetic conditions, with mutations in the BRCA1 and BRCA2 genes and Lynch syndrome-related genes occurring in approximately 1 in 500 and 1 in 370 individuals, respectively." (PMID 30651894, 2019). "Seventy-six patients—31% of all pathogenic variant carriers—had a germline mutation in BRCA1 and/or BRCA2, and 39 (16%) had a pathogenic variant in a mismatch repair gene conferring a diagnosis of Lynch syndrome." (PMID 34322651, 2019). "Four out of eleven tumors revealed a BRCA mutation (two cases with BRCA1 mutations, one case with a BRCA2 mutation and an additional case with known Lynch-syndrome showing co-occurrence of BRCA1 and BRCA2 mutations)." (PMID 30717682, 2019).
Lynch syndrome (continued). "The tumor of a fourth patient with known Lynch-syndrome revealed a BRCA1 as well as a BRCA2 mutation both classified as class 3 mutations and therefore probably not therapeutically important." (PMID 30717682, 2019). "The genetic mutations and syndromes that are linked to PDAC include Peutz-Jeghers syndrome, Lynch syndrome, p16 carriers, BRCA2 mutation, and PALB2 mutation carriers." (PMID 27069714, 2016). "BRCA1 and BRCA2 together accounted for 50.5% of all positive findings, Lynch syndrome genes for 14.3%, and moderate or less well-defined risk genes for 33.0%." (PMID 26681312, 2016). "U.S. screening recommendations now include men with high-risk germline mutations (such as BRCA2 or Lynch syndrome MMR genes) or high-risk ancestry (e.g., African or Ashkenazi Jewish heritage) within the “high-risk” category for earlier PSA-based screening, typically in the 40s." (PMID 41440226, 2025). "Risk-reducing gynecological surgery (RRGS) is a prophylactic procedure that may be offered to BRCA1, BRCA2, and Lynch syndrome (LS) mutation carriers to reduce the risk of developing gynecological cancer." (PMID 38698439, 2024). "Identifying a germline pathogenic variant in PDAC is important as it may allow targeted therapies such as Poly ADP-ribose polymerase (PARP) inhibitors in those with BRCA1/BRCA2 pathogenic variants and immunotherapy in Lynch syndrome." (PMID 34399810, 2021). "Cancer survivors with a family history of cancer may be at high risk of SPC, with most common syndromes identified to date including mutations in BRCA1 and BRCA2 genes and Lynch syndrome." (PMID 24528929, 2014). "In addition, woman with a suspected high-risk hereditary cancer syndrome (BRCA1 and BRCA2 mutation and Lynch syndrome) should receive genetic counselling, and, if the mutation is confirmed, to consider prophylactic surgery (risk-reducing bilateral salpingo-oophorectomy)." (PMID 29966369, 2018). "Recommended gene panels prioritize DNA repair and Lynch syndrome genes—with BRCA2, BRCA1, and MMR genes as top targets in metastatic disease." (PMID 41440226, 2025). "The genes with the highest prevalence of P/PV variants included CHEK2 (26%), MUTYH (21%), BRCA2 (8%), APC I1370K (8%), and Lynch Syndrome-associated (7%)." (PMID 40770526, 2025). "Low numbers of self-identified Black patients precluded statistical testing; however, PGV rates were nominally higher in BRCA2 and the Lynch syndrome genes." (PMID 40832411, 2025). "BRCA2+, Lynch Syndrome) were all considered, in addition to CA125 and the previously calculated scores for ultrasound, RMI2, and MMP index." (PMID 38893167, 2024). "From 5605 records reviewed, 9 studies (4 randomised control trials and 5 cohort studies) were included involving families with BRCA1, BRCA2 and Lynch syndrome." (PMID 36253533, 2023).
Lynch syndrome (continued). "Six males carried genetic mutations: four patients had a BRCA2 mutation, one patient a CHECK2 mutation, and one patient presented MLH1 mutation (associated with Lynch syndrome)." (PMID 37999136, 2023). "Various case reports have identified IPMNs in patients with polycystic kidney disease, Lady Windermere Syndrome, parathyroid adenoma concerning for multiple endocrine neoplasia type 1 or type 2A, cystic fibrosis, BRCA2 and Lynch syndrome." (PMID 35884779, 2022). "High-risk groups are patients with a positive family history of PC, hereditary PC, familial atypical multiple mole melanoma (p16 mutation), cystic fibrosis, Peutz–Jeghers syndrome, Lynch syndrome and HBOC (BRCA1/BRCA2 mutation)." (PMID 31717773, 2019). "This is especially important given the largely debated topic of population screening for BRCA1, BRCA2, and Lynch syndrome." (PMID 31266460, 2019). "Across unaffected populations, fewer than 5% of BRCA1 or BRCA2 carriers and fewer than 1% of Lynch syndrome carriers are estimated to have been identified through genetic testing." (PMID 30651894, 2019). "Those with a pathogenic variant in CDKN2A, BRCA2, PALB2, or a Lynch syndrome-associated gene and a first degree relative are potential candidates for screening." (PMID 30186770, 2018). "Michigan used cancer registry data from 2006 through 2007 to identify more than 15,000 people needing evaluation for BRCA1 or BRCA2 or Lynch syndrome by the end of 2012." (PMID 24921900, 2014). "Similarly to studies on Western populations, mutations in genes other than those associated with the Lynch syndrome, including MUTYH, BRCA2, ATM, BRIP1, CDKN2A, and NF1, were identified." (PMID 39061183, 2024). "The most significant risk factor for OC development are germline pathogenic/likely pathogenic variants (GPVs) in OC predisposition genes (including BRCA1, BRCA2, BRIP1, RAD51C, RAD51D, Lynch syndrome genes, or BRIP1), which contribute to the development of over 20% of all OC cases." (PMID 38069345, 2023). "Similarly, BRCA1, BRCA2 and PMS2 were also reported as germline mutations in cancers other than Lynch syndrome and HBOC." (PMID 36451132, 2022). "Furthermore, a combined 27% of participants who had genetic testing reported a mutation in BRCA1 (12%), BRCA2 (7%) or in another OC gene (8%; most commonly RAD51C/D, CHEK2 and the Lynch Syndrome genes)." (PMID 35621661, 2022). "Also, 78% and 62% of respondents were aware of the association between hereditary PC and BRCA2 mutations (BRCA2m) and BRCA1 mutations, respectively, but < 40% were aware of the association between hereditary PC and Lynch syndrome." (PMID 35924163, 2022).
Lynch syndrome (continued). "These services included testing for the BRCA1 or BRCA2 mutation in patients without cancer who met US Task Force on Preventive Services guidelines as well as genetic testing for Lynch syndrome according to National Comprehensive Cancer Network guidelines." (PMID 24921900, 2014). "These panels usually include DNA damage-repair genes (e.g., BRCA1, BRCA2, ATM, CHEK2, PALB2), mismatch-repair genes (Lynch syndrome), and syndrome-specific genes such as VHL, FH, FLCN, and MET." (PMID 41440226, 2025). "The percent of germline LP/P variants within the traditional genetic counseling and tumor DNA safety net groups was similar for BRCA2 (40% versus 32%), PALB2 (3% versus 8%), and Lynch syndrome genes (collectively 19% versus 13%)." (PMID 36261688, 2023). "Conversely, by testing families suspected to have Lynch Syndrome for 112 known or candidate colorectal cancer genes, Hansen and colleagues identified one BRCA1 carrier and two BRCA2 carriers." (PMID 28637432, 2017). "Moreover, the results of OC surveillance in women with BRCA1 and BRCA2 mutations may not be directly applicable to Lynch syndrome due to significant biological differences between OC in Lynch syndrome and OC seen in hereditary ovarian and breast cancer syndrome." (PMID 39768893, 2024). "Of note, the patient portal does not capture information beyond the scope of BRCA1 and BRCA2—associated HBOC, such as Li‐Fraumeni syndrome, Lynch syndrome or more moderate‐risk HBOC genes." (PMID 36660874, 2023). "The PV carriers in Lynch syndrome genes and BRCA1/BRCA2 could benefit from treatment with immune checkpoint (PD-1/PD-L1 inhibitors) and PARP (PARPi) inhibitors, respectively." (PMID 36612198, 2022). "PVs in BRCA1, but not BRCA2, PALB2, ATM, CHEK2, or Lynch syndrome genes, were associated with elevated RS on multivariable analysis (P < .001)." (PMID 33426465, 2021). "For patients without Lynch syndrome, APC was identified as the gene associated with the most mutations (n = 14) and was followed by BRCA1 (n = 8), RAD50 (n = 7), MUTYH (n = 5), ATM (n = 5), and BRCA2 (n = 4)." (PMID 35014770, 2022).